DHX9 (DExH-box helicase 9)
Diseases named in the same sentence as DHX9 in open-access papers (continued):
Sharing a sentence is not in itself a finding about the gene and the disease.
cancer (continued). "Previously, we reported that, in certain human cancer cells, knockdown of DHX9 using RNAi significantly enhanced MYXV replication, suggesting that DHX9 is capable of mediating antiviral functions against MYXV." (PMID 33952639, 2021). "Among them, we want to highlight DDX3 as a confirmed target for cancer and antiviral therapy, while others, like DDX46, DHX9 and DDX5, are still poorly studied in this context." (PMID 33804185, 2021). "In the present study, our focus was to understand how RHA/DHX9, a key member of cellular RNA helicases, restricts MYXV infection and replication in a subset of MYXV-resistant or semipermissive human cancer cell types." (PMID 33952639, 2021). "In particular, the involvement of DHX9 in neurodevelopmental disorder and several hallmarks of cancer are not captured by GO annotations because (i) these roles are due to an interaction of DHX9 with other partners and (ii) GO is not a disease ontology." (PMID 40338520, 2025). "DEAH box helicase 9 (DHX9), also known as nuclear DNA helicase II, has been shown to constitute a bidirectional regulatory mode in adenosine-to-inosine (A-to-I) editing, which is partially responsible for the dysregulation of editing spectrum in cancer." (PMID 39726754, 2024). "And increased DHX9 blocks the DNA repair function of BRAC and leads to cancer development." (PMID 37214432, 2023). "DHX9, an NTP-dependent DNA and RNA helicase, is dysregulated in a variety of cancers." (PMID 37550275, 2023). "Importantly, inhibition of the interaction of DHX9 with members of the ETS transcription factor family displayed powerful anti-tumor effects on the growth and progression of several cancer types, including PC." (PMID 35590370, 2022). "Our results clearly demonstrate that, unlike RNA viruses, DHX9 formation of the cytoplasmic granular structures in human cells can significantly restrict MYXV replication in at least a subset of human cancer cells." (PMID 33952639, 2021). "Here, we report a novel antiviral function of DHX9, where it forms “antiviral granules” in the cytoplasm that can restrict MYXV in at least some human cancer cells by sequestering essential viral factors and thus restricting late stages of the replication cycle." (PMID 33952639, 2021). "In these nonpermissive cancer cell lines, apart from DHX9 antiviral granules, other signaling pathways or cellular factors, for example, the level of activated/phosphorylated AKT, also contribute to the restrictive replication of MYXV." (PMID 33952639, 2021). "Moreover, most identified helicases, including DHX9 and DDX5, showed mRNA overexpression in a range of cancers, based on the ONCOMINE database." (PMID 29742442, 2018). "Thus, it is reasonable to speculate that SLFN11 epigenetic silencing compromises the correct partnership of DHX9 and BRCA1, and then it alters the correct function of the DNA damage response system, causing a shift in the platinum-associated chemosensitivity of the affected cancer cells." (PMID 26625211, 2016). "Thus, oncogenic MYCN levels globally suppress circRNA expression at least in part by aberrantly upregulating the DHX9 RNA helicase, suggesting that this may be a common mechanism in MYCN-driven cancers." (PMID 37402719, 2023). "Another possibility is that DHX9-mediated antiviral pathways are fully operational in certain cancer cell types and defective in many, if not most, human cancer cells, thus allowing greater levels of MYXV replication than in their normal somatic cell counterparts." (PMID 33952639, 2021). "Recent studies suggest that DNA sensors such as AIM2, TLR9, DHX9, DHX36 and adaptor STING may have roles in CRC development, and the other DNA sensors such as DDX41, DDX60, IFI16, and DAI participate in the development of other types of cancers." (PMID 31949493, 2020). "However, DHX9 and other DEAD/H helicases also may be upregulated in cancer to prevent R-loop accumulation or to promote the restart of replication forks stalled by the excess of R-loops." (PMID 29742442, 2018).
cancer (continued). "In the case of MYXV, we previously identified DHX9 / RNA helicase A (RHA) as a host protein that physically interacts with the viral host range factor M029, which also interacts with host cellular PKR, modulating MYXV tropism in a number of tested human cancer cells." (PMID 29146961, 2017). "Therefore, DHX9’s involvement in circCCDC66 regulation, and putative cross-talk with FAK phosphorylation and EMT upon DHX9-mediated circPICALM suppression, further implicates it in cancer cells’ acquisition of a mesenchymal phenotype and enhanced invasive features." (PMID 33437516, 2020). "We previously reported that in certain types of human cancer cell lines (particularly those that are naturally semipermissive or nonpermissive for MYXV), DHX9 knockdown enhanced progeny virus formation." (PMID 33952639, 2021). "Furthermore, DHX9 knockdown significantly enhanced MYXV replication in both semipermissive and nonpermissive human cancer cell lines." (PMID 37377603, 2023). "We also used the GEPIA2 database to analyze the correlation between DHX9 expression and clinicopathological stages of various cancers and found there was a statistical difference in ACC, LIHC and SKCM, while most other cancers showed no statistical difference." (PMID 37214432, 2023). "In addition, we show that in the absence of DHX9, the formation of DHX9 antiviral granules can be inhibited, which significantly enhanced oncolytic MYXV replication in human cancer cell lines where the virus is normally restricted." (PMID 33952639, 2021). "Like many RNA helicases, DHX9 is important in numerous cellular processes, ranging from mRNA processing to resolution of R-Loops, and has been shown to promote antiviral immunity by activation of the IFN-I, though those studies were not performed using cancer cell lines." (PMID 38530197, 2024).
tumor (74 papers, 2012 to 2025). "DHX9 has also been implicated in the development of prostate cancer, and can have both oncogenic and tumor suppressor functions in lung cancer." (PMID 39620586, 2025). "DHX9 functions as a oncoprotein that is closely associated with tumor cell proliferation and metastasis." (PMID 38041141, 2023). "DHX9 has been implicated in many cellular processes, including regulation of DNA replication, transcription, translation, RNA processing and transport, tumor cell maintenance and drug response." (PMID 37415734, 2023). "Approximately 78% of the globally downregulated circRNAs in MYCN-amplified high-risk tumor samples were upregulated by DHX9 knockdown in our cell model." (PMID 37402719, 2023). "Taken together, these results suggest that DHX9 plays an important role in PC by supporting oncogenic features associated with the tumor phenotype." (PMID 35590370, 2022). "RNF168 depletion led to a further increase of R-loop levels and reduced tumour formation in BRCA1-mutated cells, indicating a functional role of DHX9 ubiquitylation in R-loop resolution and tumour formation of BRCA1-deficient backgrounds." (PMID 33755171, 2021). "DHX9 has been implicated in tumor cell maintenance by participating in transcriptional and translational steps and DNA replication." (PMID 28460433, 2017). "Furthermore, DHX9 expression exhibited strong correlations with immune cell infiltration, immune checkpoint genes, and tumor mutational burden (TMB)/microsatellite instability (MSI)." (PMID 37214432, 2023). "DHX9 has been implicated in tumor cell maintenance and drug response." (PMID 35600388, 2022). "The DHX9-suppressing tumor cells may gain advantages from the deficient RNA processing-induced oncogenic circRNAs and escape from the therapeutic treatment against DHX9." (PMID 32187976, 2020). "Tumor xenografts exhibited a significant reduction upon DHX9 knockdown compared with the EV control group." (PMID 39941810, 2025). "Damaged DHX9 can promote the expression of oncogenic circRNAs, which help tumor cells escape from the genotoxic stress response." (PMID 40290118, 2025). "In HCC tissues, conspicuous upregulation of DHX9 expression has been observed, which correlates with the progression of tumor stages." (PMID 39941810, 2025). "Inhibition of DHX9 induces cellular dsRNA accumulation and triggers tumor intrinsic innate immunity." (PMID 39941810, 2025). "In ADAR1-dependent BC cell lines, the knockdown of DHX9 led to PKR activation and cell death, underscoring a cooperative role between ADAR1 and DHX9 in suppressing innate immune activation and promoting tumor cell survival." (PMID 40852728, 2025). "In HCC, elevated DHX9 levels have been correlated with tumor node metastasis (TNM) stage, vascular invasion, and metastasis, serving as independent factors for poor prognosis." (PMID 39941810, 2025). "PBX1-rG4 edited cell lines showed no dependence on rG4-stabilizing compounds, and immunohistochemistry of normal and tumor tissues revealed that DHX9 absence corresponded to PBX1 absence." (PMID 39940956, 2025). "DHX9 can also have varied oncogenic and tumor suppressor activities due to its ability to regulate transcription of a number of oncogenes and tumor suppressors, as well as modulate the activity of the resulting proteins." (PMID 39620586, 2025). "The contextual variability in DHX9’s functional role underscores its tumor-specific tumorigenic properties." (PMID 39941810, 2025). "Tumor tissues from EV and shDHX9 groups were stained for pAKT, and the results showed that DHX9 knockdown in vivo resulted in downregulation of pAKT expression." (PMID 39941810, 2025). "DHX9, the top hub gene with the highest kME in the blue module, has been found to be relevant to defection of alternative splicing in tumor cells and promotes the formation of R-loop structures of nucleic acids." (PMID 37492578, 2023). "The potential relationship between DHX9 and tumor immune microenvironment remains insufficiently explored." (PMID 37214432, 2023).
tumor (continued). "Consistent with the DHX9 expression pattern, the expression level of TGFβR1 in tumor tissues was significantly higher than that in normal tissues." (PMID 37214432, 2023). "In human gliomas, DHX9 expression has been shown to increase and promote tumor cell proliferation, migration and invasion." (PMID 38275375, 2023). "Recent studies have reported that RNA helicases play a role in the progression of a variety of tumor types, including DHX9, DHX15, DDX24, DHX29, and DHX36." (PMID 37958405, 2023). "In this study, we used CPTAC to analyze data from 6 tumor types and found that the DHX9 phosphorylation level of site S449 was significantly lower only in ccRCC compared with normal tissues." (PMID 37214432, 2023). "The Ki‐67 staining of tumor tissue sections indicated that ki‐67 positive‐stained cells decreased in the DHX9 knockdown groups." (PMID 36377508, 2023). "The expression of the DHX9 was significantly higher in tumor tissues than in adjacent normal tissues in both LIHC, LUAD and BRAC." (PMID 37214432, 2023). "In vitro, suppression of DHX9 expression led to the downregulation of CSF1, suggesting that DHX9 should be considered as another potential target for immunotherapy, which is related to the known tumor suppressive effect of the downregulation of CSF1." (PMID 38275375, 2023). "The expression levels of DHX9 were then verified in tumor specimens by western blot and immunohistochemistry (IHC)." (PMID 37214432, 2023). "Our results revealed that the DHX9 expression in PDAC was significantly associated with lymph node metastasis and tumor TNM stage." (PMID 36578944, 2022). "circDCUN1D4 is downregulated in tumor samples under the mediation of DExH-box helicase 9 (DHX9), which inhibits the formation of circRNA by binding inverted repeat Alus (IRAlus) in flanking sequences." (PMID 33425493, 2021). "DHX9 upregulation induces cSMARCA5 downregulation, suppressing its tumor suppressive functions to promote HCC progression and metastasis." (PMID 33437516, 2020). "With this in mind, an aptamer-targeting DHX9 has been identified for use in CRC tumor cells in vivo." (PMID 33437516, 2020). "Much interest has been expended lately in characterizing the association between DExH-Box helicase 9 (DHX9) dysregulation and malignant development, however, the enigmatic nature of DHX9 has caused conflict as to whether it regularly functions as an oncogene or tumor suppressor." (PMID 33437516, 2020). "This highlights the tumor suppressive role of DHX9 in modulating p16INK4a transcription on cell cycle control." (PMID 33437516, 2020). "This work further highlights the context-dependent manner of DHX9 in promoting either tumor suppression or tumorigenesis and adds another layer of contradiction to this enigmatic helicase." (PMID 33437516, 2020). "For example, DHX9 expression in bladder cancer (BC) tissue suppresses circPICALM action, which usually functions as a tumor suppressor by ‘sponging’ for miR-1265, preventing FAK phosphorylation and EMT." (PMID 33437516, 2020). "This is a prime example of how DHX9 overexpression can overcome tumor suppressive protection in BC and negatively influence EMT to promote BC invasion and metastasis." (PMID 33437516, 2020). "DHX9 has several interacting partners that are directly involved in DNA repair, the most prominent being the tumor suppressor BRCA1." (PMID 26625211, 2016). "This suggests that while ATG5, as one of the core components of the autophagy-initiating machinery, may be required for BECN1-mediated tumor-suppressive effects of DHX9 silencing, only BECN1 functions as the essential triggering factor." (PMID 40659605, 2025). "Moreover, both tumor weight and growth trajectory indicated pronounced inhibition of tumor progression post-DHX9 knockdown." (PMID 39941810, 2025). "The results showed DHX9 inhibition markedly extended the survival time of the tumor-bearing mice." (PMID 40659605, 2025).
tumor (continued). "Interestingly, similar to BECN1 knockdown, ATG5 silencing also reversed the autophagy-promoting and tumor-suppressive effects of DHX9 silencing." (PMID 40659605, 2025). "Such incongruities underscore that DHX9’s interactions with the AKT pathway might be tumor-type-specific, potentially rationalizing DHX9’s disparate roles across malignancies." (PMID 39941810, 2025). "Meanwhile, reduced DHX9 expression postponed tumor development both in vitro and in vivo." (PMID 40659605, 2025). "As expected, DHX9 knockdown obviously reduced tumor growth, volume and weight." (PMID 40659605, 2025). "Interestingly, although CQ functions as an autophagy inhibitor, which is opposed to DHX9 silencing-induced autophagy activation, our study showed the enhanced tumor-inhibitory effects upon their combined application." (PMID 40659605, 2025). "Furthermore, Dhx9, Dusp12, Fhl1, and Ifitm1 are each correlated with the invasion of tumor‐infiltrating immune cells into the microenvironment." (PMID 38193115, 2024). "Therefore, we investigated the role of DHX9 in tumorigenesis using a model of intestinal adenomatosis, employing the well-established Apcmin/+ mouse tumor model." (PMID 38594251, 2024). "Notably, tumour cells exhibit a higher dependency on DHX9, while systemic knockdown is well-tolerated in adult mice, making DHX9 a potential therapeutic target." (PMID 39435974, 2024). "In addition, DHX9 facilitates the infiltration of macrophages into tumor tissues and their polarization to the immunosuppressive M2 type by upregulating colony-stimulating factor 1 (CSF1)." (PMID 38275375, 2023). "In addition, as a downstream gene of SOX4, DHX9 activates the Wnt/β-catenin signaling pathway then promotes tumor metastasis and drug resistance." (PMID 37214432, 2023). "These divergent functions might be attributable to differences in cell type, tumor heterogeneity, or other unknown factors, suggesting the complexity of DHX9 in carcinogenesis." (PMID 37041291, 2023). "Besides, in 6 pairs of LIHC samples, the expression level of DHX9 in tumor tissues was significantly upregulated." (PMID 37214432, 2023). "Besides, DHX9 is a multi-domain and multi-functional enzyme, when it is deregulated, it can alter cellular growth and result in tumor formation." (PMID 37214432, 2023). "Furthermore, subcutaneous xenograft tumor model was established and revealed that the knockout of DHX9 markedly suppressed the growth of Hep-3B cells." (PMID 37214432, 2023). "DHX9 is a highly conserved DExD/H-box protein, expressed in the nucleus and the cytoplasm, involved in many processes including transcriptional activation, RNA editing, microRNA biogenesis and tumor cell maintenance." (PMID 37041291, 2023). "Moreover, DHX9 expression was evaluated in human tumor specimens from stable and progressive disease, with complete or partial remission, from the same TCGA dataset, undergoing or not biochemical recurrence." (PMID 35590370, 2022). "DHX9 is an indispensable regulatory in transcription and translation, DNA replication, and maintenance of genomic stability, and the experiments in vivo and in vitro demonstrate that DHX9 suppression can conduce to tumor inhibition." (PMID 35047095, 2022). "Because of the involvement of DHX9 in multiple cellular processes, including DNA replication, transcription, translation, microRNA biogenesis, RNA processing and maintenance of genomic stability, accumulative studies reveal that DHX9 exerts dual effects on tumor development." (PMID 36402769, 2022). "In contrast, during the late stage of tumorigenesis, upregulation of DHX9 expression can elicit complex effects on tumor development that may be in a cellular context-dependent manner." (PMID 36402769, 2022).